IL4 (interleukin 4)
Diseases named in the same sentence as IL4 in open-access papers (continued):
Sharing a sentence is not in itself a finding about the gene and the disease.
eosinophilia (continued). "Finally, we showed that i.n. challenge with recombinant human IL-4 or human IL-13 leads to eosinophilia, lung inflammation, and mucus production in hIL-4/hIL-13KI; hIL-4RαKI mice." (PMID 33976140, 2021). "The observed rise in blood eosinophilia was hypothesized to be due to the inhibition of IL-4/IL-13 signaling." (PMID 34572281, 2021). "Our previous study has demonstrated that the activation of Tc2 cells could contribute to airway eosinophilia through producing proinflammatory cytokines IL-4/5/13 and GM-CSF." (PMID 34011519, 2021). "However, type 2 inflammation characterized by production of interleukin-4 (IL-4) and IL-13 in the lung, airway eosinophilia, and high levels of IgE antibodies occurs in ~50% of patients with asthma." (PMID 33976140, 2021). "Previous studies have demonstrated that cytokines such as IL-2, IL-4 could recruit eosinophils and lead to eosinophilia and enhanced eosinophil activation, thereby exert potent anti-tumor immune responses." (PMID 32434481, 2020). "In addition to ILC2, basophils, mast cells, and eosinophilia constitute IL-4– and IL-13–producing cells of the innate immune system during lung helminth infection." (PMID 33193446, 2020). "Since tissue eosinophilia is governed by the production of cytokines such as IL-5 and to a lesser extent by IL-13 and IL-4, it is assumed that eosinophilia either in the blood compartment or in the bronchi of asthmatic patients is a reflect of type 2 inflammation." (PMID 32296705, 2020). "The production of type 2 cytokines (IL-4, IL-5, IL-10, and IL-13), as well as granulocyte-macrophage colony-stimulating factor (GM-CSF), by these cells induces eosinophilia, M2 macrophage polarization, and the secretion of immunoglobulin G1 (IgG1), IgG4, and IgE." (PMID 33013887, 2020). "Moreover, IL-4 has been shown to boost the airway eosinophilia induced by IL-5 in mice sensitized/challenged with OVA." (PMID 31805682, 2019). "We could also compare the reduction of the IL-4 levels with lower lung eosinophilia once there is evidence, suggesting that this cytokine increases airway eosinophilia." (PMID 31156611, 2019). "Because rIL-4 delivery can induce pleiotropic effects on IL-4 responsive cell types, which could influence tissue eosinophilia, we addressed the specificity of BmL3AAMφ by ablating Mφ prior to rIL-4 delivery and infection." (PMID 29547639, 2018). "Furthermore, HDM-treated C57BL/6Mthfr-/- mice compared to HDM-treated C57BL/6 mice have reduced whole lung lavage (WLL) cellularity, eosinophilia, and Il-4/Il-5 cytokine concentrations." (PMID 29329322, 2018). "IL-4 can induce eosinophilia gathering, inflammation, and exacerbate the rejection response." (PMID 29576879, 2018). "Eosinophilic bronchitis is usually a Type 2 (T2)-driven process and therefore a sputum eosinophilia of greater than 3% usually indicates a response to treatment with corticosteroids or novel therapies directed against T2 cytokines such as IL-4, IL-5, and IL-13." (PMID 29018800, 2017). "The rise in levels of parasite-specific IL-4 after TGF-β inhibition suggests that TGF-β may be responsible for inhibiting IL-4-dependent anti-parasitic mechanisms during acute infection, such as eosinophilia or mastocytosis." (PMID 28362822, 2017). "Taken together, lower TGF-β1 levels in lungs with NP-CpG may be a consequence of lower eosinophilia and Th2-related cytokine production (IL-4, IL-5, IL-13) in NP-CpG treated mice." (PMID 26387548, 2015). "In an OVA+Alum sensitization model, intranasal lunasin treatment at the time of OVA challenges significantly reduced total cells counts in bronchoalveolar lavage (BAL) fluid and eosinophilia, peribronchiolar inflammatory infiltration, goblet cell metaplasia and airway IL-4 production." (PMID 25646897, 2015).
eosinophilia (continued). "On the other hand, our findings that late-stage EMF patients display increased IL-4 and IL-10 levels are also consistent with the observed early eosinophilia and helminthic infections in EMF, once this type of infection is usually associated with increased levels of these cytokines." (PMID 25303100, 2014). "Interestingly, the same studies showed IL-4 and IL-13 to be potent inducers of airway eosinophilia, whereas in our study, airway hyporesponsive, highly eosinophilic OVA/CFA sensitized mice had comparatively lower BAL fluid levels of both cytokines." (PMID 25123451, 2014). "The protection observed in mice correlated with ES-62-induced desensitisation of mast cells, which have been implicated in airway remodelling, and also with suppression of the Th2 phenotype of airway inflammation, the latter as evidenced by reduced eosinophilia and IL-4 levels in the lungs." (PMID 23291461, 2013). "Previous studies have also demonstrated that eosinophilia occurs between the 5th and 7th weeks after exposure to the parasite and may be induced by Th2 cytokines, such as IL-4, IL-10, IL-13, IL-9, and especially IL-5." (PMID 23401741, 2013). "Dysregulated type 2 immunity in allergic asthma is characterized by an expansion of CD4+ Th2 cells and cytokines (IL-4, IL-5, IL-13), elevated total and allergen-specific IgE, eosinophilia, and airway inflammation and a counterbalance emergence of B1a cells with regulatory capacity." (PMID 23840604, 2013). "Further assessment involving the co-administration of IL-4 and IL-2 resulted in eosinophilia of unknown significance in all patients studied." (PMID 22251275, 2012). "Therefore, because of the reduction in nasal mucosa eosinophilia, IL-4 and IL-5 levels in NLF, and OVA-specific IgE levels in sera, 2ME2 treatment likely inhibits the nasal allergic responses." (PMID 23133644, 2012). "The increase in IL-5 and IL-4 may be responsible for the possible eosinophilia and elevation of serum immunoglobulin E levels, respectively, in HIV-related eosinophilic diseases like eosinophilic folliculitis and EP." (PMID 23148793, 2012). "Increased IL-10 levels could explain the reported reductions in IL-4 and IL-5 as well as the inhibition of eosinophilia, since IL-10 has been shown to downregulate IL-4 and IL-5 expression by Th2 cells and reduce eosinophil survival." (PMID 22966222, 2012). "Progesterone, on the other hand, significantly increases the expression of IL-10, IL1-β, and TNF-α in the lungs, and augments the release of IL-4 by bone marrow cells, which may lead to eosinophilia." (PMID 21639909, 2011). "Taken together, the observed reduction in airway eosinophilia by artesunate may be a result of combined inhibitory effects on IL-4, IL-5, IL-13, eotaxin and RANTES production, and on adhesion molecule expression, secondary to inhibition of PI3K/Akt." (PMID 21695271, 2011). "Instillation of chitin micro-particles into the airways significantly down-regulated allergic responses to Dermatophagoids pteronyssinus (Der p) and Aspergillus fumigatus including IgE levels, IL-4 production, eosinophilia, airway hyper-responsiveness, and lung inflammation." (PMID 21383982, 2011). "Additionally, infecting neonates with recombinant RSV expressing IFN-γ was found to abrogate disease enhancement, while RSV expressing IL-4 resulted in further enhancement of Th2 responses and eosinophilia." (PMID 22144888, 2011). "Allergic asthma is caused primarily by an inappropriate CD4+ Th2 response, which results in symptoms mediated by Th2 cytokines, including IL-13 provoking airways hyperresponsiveness and mucus production, IL-4 promoting the production of antigen specific IgE, and IL-5 inducing eosinophilia." (PMID 20659336, 2010). "Eosinophilia is driven by Th2 cytokines (e.g., IL-4, IL-5, IL-13) produced by Th2 cells." (PMID 19657453, 2009).
eosinophilia (continued). "IL-4 and IL-13 are critically involved in the pathogenesis of allergic asthma by regulating IgE-production by B cells, inducing airway hyperreactivity and triggering key features of airway remodeling, whereas IL-5 is a key factor for eosinophilia." (PMID 18724870, 2008). "Perhaps this low rate is explained by the chronicity of the disease with eosinophilia being present only early in the course via stimulation of Th2 lymphocytes and production of IL-4 and IL-5 subsequently generating IgG1 and IgE-secreting cells, and eliciting eosinophilia." (PMID 15904502, 2005). "In this case, the marked elevation of anti-Dsg1, eosinophilia, and dermal eosinophilic infiltrate suggest that IL-17A inhibition may have downregulated the Th1/Th17 axis, relieving inhibition of Th2 cells and promoting IL-4/IL-13 elevation." (PMID 41000395, 2025). "Nevertheless, by analogy with dupilumab-induced IL-4/13 blockade, the persistence of sputum eosinophilia (reported in both patients) raises questions as to whether TSLP inhibition could lead to a rebound of eosinophilia and potentially to eosinophil-related symptoms in patients with EGPA." (PMID 38992639, 2024). "Therefore, assessment of IL-4 levels, eosinophilia and soluble VE-cadherin as a possible surrogate marker for endothelial barrier dysfunction might be useful tools to distinguish pirfenidone responders from patients at risk of disease exacerbation." (PMID 35332068, 2022). "Interestingly, L.rhamnosus maternal supplementation resulted in decreased eosinophilia and neutrophilia in the bronchoalveolar lavage (BAL) fluid and in decreased Th2-associated cytokines mRNA transcripts (i.e., Il4, Il5 and Il13) in the lung of neonatally sensitized mice." (PMID 36685549, 2022). "Indeed, L.rhamnosus supplementation inhibited the lung eosinophilia (with no impact on neutrophil and lymphocyte numbers) and the Th2-associated mRNA transcripts (i.e., Il4 and Il5 and a trend for Il13) in mice neonatally sensitized with OVA." (PMID 36685549, 2022). "Impaired tissue homing might be the cause for blood eosinophilia, as migration of eosinophils to tissues, but not their bone marrow egress or production, is dependent on IL-4/IL-13-induced eotaxins and vascular-cell adhesion molecule-1." (PMID 32344789, 2020). "Specifically targeting DCs to modulate CD4+ T cell responses may represent a promising approach to treat allergic asthma where an enhanced Th2 response frequently leads to IgE production (IL-4), eosinophilia (IL-5), mast cell activation (IL-9), and AHR (IL-13)." (PMID 28439267, 2017). "In addition, substantial evidence exists from in vitro cell culture models, in vivo animal models and observational human studies for the role of IL-13 (and IL-4) in driving eosinophilia and type 2 inflammation, which led to interventional studies targeting these pathways in human disease." (PMID 29034234, 2017). "Thus, on one hand Cd300f−/− mice display elevated eosinophilia which secrete increased levels of IL-4 and on the other hand, Cd300f−/− macrophages may be less responsive to IL-4, which may cause them to promote obesity and glucose intolerance." (PMID 28725048, 2017). "Recent studies have clearly defined the differential roles of IL-4 and IL-13 in allergic inflammation; IL-4 preferentially regulates Th2 cell function and IgE synthesis, whereas IL-13 mediates the pathophysiological processes that control mucus production, eosinophilia and AHR." (PMID 26740570, 2016). "It is known that IgE and IgG4 responses are elicited by IL-4, while IFN-γ and eosinophilia are stimulated through IL-3 and IL-5." (PMID 40041800, 2025). "Itepekimab, an anti-IL-33 antibody, effectively engages its target and mitigates tissue eosinophilia, while CM310-stapokibart, tralokinumab, and lebrikizumab inhibit IL-4/IL-13 signaling with variable efficacy depending on patient biomarkers." (PMID 40732309, 2025).
eosinophilia (continued). "CRSwNP-dominant regulators are engaged in T2 inflammation or eosinophilia, such as ERBB, TNF pathway, inflammatory and host defense, cytokine regulators and their cytokines, such as CSF2 or IL4, and angiogenetic factors." (PMID 36982612, 2023). "This also reduced their expression of Gata3, Il4, Il5, and Il13 in lung conventional CD4+ T cells: these effects markedly reduced the eosinophilia and AHR." (PMID 37917548, 2023). "The protective effect of Hp‐TGM on airway eosinophilia was also obtained in the longer T‐cell mediated models of HDM or OVA sensitisation with significant inhibition of eotaxin‐1, IL‐4 and IL‐13 responses depending on the model and time‐point." (PMID 35758054, 2022). "We demonstrate that vaccination against IL-4 and IL-13 is well tolerated and protects against key features of chronic asthma in mice, including AHR, eosinophilia, and mucus overproduction, after both prophylactic or therapeutic vaccination protocols." (PMID 33976140, 2021). "Allergic asthma is characterized by elevated levels of IgE antibodies, type 2 cytokines such as interleukin-4 (IL-4) and IL-13, airway hyperresponsiveness (AHR), mucus hypersecretion and eosinophilia." (PMID 33976140, 2021). "Recently, we have defined a mechanism of adaptive immune control against invading B. malayi filarial larvae that is mediated by IL-4–IL-4R alternative activation of peritoneal macrophages and resultant CCR3-dependent tissue eosinophilia." (PMID 32571840, 2020). "The immune response of sheep against GIN infections is primarily associated with the adaptive Th2-polarized profile, with local release of the interleukins IL4, IL5, and IL13, in addition to IgE production, eosinophilia, and mastocytosis." (PMID 31815153, 2019). "These alarmins are known to be natural triggers and enhancers of the Th2 type immune response, resulting in local and systemic induction of IL4, IL5, and IL13 synthesis, eosinophilia, and high levels of IgE." (PMID 31815153, 2019). "The parasitological outcome of IL-4/IL-4Rα activation of BmL3AAMφ and CCR3-dependent tissue eosinophilia was a significant reduction in B. malayi larvae in SCID mice +14dpi." (PMID 29547639, 2018). "The production of IL-5, IL-4, and IFN-γ cytokines in peripheral blood were evaluated on the 18th day after infection, during the peak of eosinophilia." (PMID 29445372, 2018). "Combined anti-IL-4 and anti-RSV siRNAs were able to significantly reduce total cell count and eosinophilia in BAL fluid, downregulate both IL-4 and RSV viral RNA expression, and attenuate AHR, but upregulate IFN-γ level in lung tissues." (PMID 28106744, 2017). "In BALB/c ovalbumin challenged mice fed daily with Bifidobacterium longum it was noted that airway inflammation was attenuated and a reduction in BAL eosinophilia, BAL fluid IL-4 protein and BAL cell IFN-γ and IL-4 mRNA levels was observed." (PMID 27919249, 2016). "The Th2 cytokines IL-4 and IL-13 bind to the IL-4/IL-13R to activate STAT-6, which plays a major role in mediating a variety of phenotypic endpoints in allergic airway inflammation, including eosinophilia, mucous cell metaplasia, and airway fibrosis." (PMID 26091108, 2015). "Therefore, not only may higher IL-4 levels at the site of inflammation be related to reduced eosinophilia in allergic tissue, but, in utero it may contribute to potential gene (e.g., atopy/IL-4) by environment (e.g., LPS) interactions which influence neonatal progenitor cell Eo/B CFU formation." (PMID 24971469, 2014). "Transgenic overexpression in mice resulted in airway eosinophilia and elevated serum levels of the typical TH2-type cytokines IL-4, IL-5, and IL-13 together with increased IgE serum titers." (PMID 20976014, 2010). "Parasite infection was confirmed by measuring signs consistent with acute schistosomiasis: egg excretion in feces, eosinophilia, and increased PBMC IL-4 mRNA levels." (PMID 18648516, 2008).
eosinophilia (continued). "Surprisingly, concentrations of canonical Type 2 cytokines IL-4, IL-5, and IL-13 were highest in the primary infection mice, despite the lack of eosinophilia." (PMID 41190814, 2025). "Similar outcomes were reported for targeting of IL-4/13 by biologics such as dupilumab, where a baseline blood eosinophilia to aid in patient selection was not always a pre-requisite." (PMID 41440490, 2025). "IL-4 stimulates the activation of GATA-3, which is a Th2 cell transcription factor, through a positive feedback loop, leading to the secretion of IgE by activating B cells, inducing eosinophilia, and stimulating airway hyperreactivity." (PMID 37569846, 2023). "In addition to increased NO levels and arginase activity, coinfected mice presented a classic Th2 anti-Sv response: eosinophilia, higher levels of alternate activated macrophages (M2), increased concentrations of CCL24 and IL-4, and lower levels of IL-1β." (PMID 37888224, 2023). "Levels of IL-4, IL-13, chemokine ligand 18 (CCL18), and thymic stromal lymphopoietin (TSLP) have been found to be elevated in AA scalp lesions, with levels of IL-4, IL-5, IL-6, CCL17, and immunoglobulin E (IgE) elevated and eosinophilia more prevalent in the serum/blood of patients with AA." (PMID 38022501, 2023). "This type 2 immune response in CRSwNP is supported by the elevation of ILC2, the increased presence of tissue eosinophilia, a clear upregulation of IL-4, IL-5, IL-13, and local IgE, and profound tissue eosinophilia independent of atopy." (PMID 35387015, 2021). "The absence of BALF eosinophilia in mye-IL4Rα−/− mice and associated reduction in BALF levels of IL-4, IL-5, and eotaxin suggest that IL4Rα expression in myeloid cells is essential for eosinophil recruitment." (PMID 34326406, 2021). "Our present study illustrates that whereas a muted eosinophil response is evident in the absence of IL-4/IL-13 signaling, low eosinophilia is still an integral component of immune attrition to juvenile adults in IL-4Rα mice." (PMID 32571840, 2020). "Furthermore, under allergic stimulation, animals with neonatal LPS treatment exhibited normal breathing patterns and IL-4 and TSLP levels, but a lower eosinophilia as compared with control group." (PMID 32379832, 2020). "Nevertheless, eosinophilia has also been observed under conditions where there was only very weak or no expression of IL-4." (PMID 33321726, 2020). "Quercetin (i.p.)supplementation for 3 days prior to OVA challenge reduced airway eosinophilia and AHR for more than 50%, while effectively lowering eosinophil peroxidase (EPO) activity and reducing pulmonary Th2/ILC2 markers GATA-3, IL-4 and IL-5, and enhancing Th1 marker T-bet." (PMID 32973501, 2020). "In the absence of IL-4, these mice were unable to mount high airway eosinophilia but presented a higher frequency of neutrophils in BALF." (PMID 33643284, 2020). "We determine that IL-4-dependent alternative activation and expansion of Mφ are essential to regulate eosinophil-dependent immunity to filarial helminth infection via amplifying and sustaining CCR3-dependent tissue eosinophilia." (PMID 29547639, 2018). "In this study, we examined if the effects of parasitic infection could be due to increased IL-5, which not only induce eosinophilia but also as a bystander effect further expands antigen-specific CD4+CD25+ Treg activated by autoantigen and IL-4." (PMID 29163523, 2017). "Neither Th2 cytokines nor the transcription factor GATA3 as well as features triggered by IL-4 (IgG1 antibodies, RELM-ß) or IL-5 (eosinophilia) could be detected in co-infected animals." (PMID 28791259, 2017). "It was reported that oxymatrine and taraxasterol could reduce the production of IL-4, IL-5, and IL-13 in bronchoalveolar lavage fluid and OVA-specific IgE in sera and inhibit OVA-induced eosinophilia in lung tissues." (PMID 28751921, 2017).